ACE (angiotensin I converting enzyme)
Diseases named in the same sentence as ACE in open-access papers (continued):
Sharing a sentence is not in itself a finding about the gene and the disease.
heart failure (continued). "We found that both ETA receptor blockade and ACE inhibition substantially reduced the extremely high heart failure-related mortality in ACF TGR." (PMID 36204993, 2023). "Heart failure is managed with ACE inhibitors, beta blockers and diuretics, rhythm abnormalities are contained depending on the type of arrhythmia." (PMID 37563298, 2023). "Comparable rates have been observed in the multicentric study ESC-HF Pilot including 5118 patients with heart failure where ACE Inhibitors or ARBs were prescribed in 88.5%, BB in 86.7%, Spironolactone in 43.7% and loop diuretics in 82.8%." (PMID 37934305, 2023). "Significant upregulation of pathway components enabled the identification of potential drug candidates used for the treatment of heart failure, such as ACE inhibitors, ARB, ß-blockers, statins and diuretics specific to the distinct MF models." (PMID 37108624, 2023). "Spironolactone and ACE inhibitors were often prescribed in patients with heart failure (heart failure represented the most common admission diagnosis in our study)." (PMID 36817138, 2023). "If heart failure develops, it is indicated to start ACE inhibitors/ARBs, mineralocorticoid receptor antagonists, and diuretics according to current guidelines." (PMID 38028484, 2023). "Pharmacological therapies, such as angiotensin-converting enzyme (ACE) inhibitors, beta-blockers, angiotensin receptor blockers (ARBs), and diuretics, have historically served as the fundamental approach to managing heart failure." (PMID 37927716, 2023). "In the presence of congestive heart failure, the standard heart failure pharmacological intervention, including ACE inhibitors, ARBs, and diuretics, is recommended." (PMID 36831060, 2023). "Risk minimization of hyperkalemia should focus on slow titration of ACE inhibitors/ARBs and spironolactone during the initiation of the treatment of heart failure (start low and go slow approach)." (PMID 36817138, 2023). "We also found that sacubitril–valsartan significantly reduces the NT-proBNP when compared to ACE inhibitors/ARBs/placebo group medications amongst heart failure patients." (PMID 36184714, 2023). "Beta blockers were used in 5 of the patients to control heart failure, while 3 patients each received ACE inhibitors, loop diuretics and spironolactone." (PMID 37563298, 2023). "Several medications have been prescribed to manage heart failure, like beta blockers, angiotensin-converting enzyme (ACE) inhibitors, calcium channel blockers (CCBs) and angiotensin receptor blockers (ARBs), without any major success in terms of efficacy." (PMID 36184714, 2023). "A few physicians mentioned that patients with heart failure should take their ACE- inhibitors for as long as possible as this gave relief from thirst." (PMID 37585424, 2023). "On average, thiazide or thiazide-like diuretics were beneficial compared to ACE inhibitors for all outcomes, except for hospitalization with heart failure in CCAE and stroke in MDCD." (PMID 36991144, 2023). "ACE inhibitors/ARBs: Angiotensin-converting enzyme (ACE) inhibitors like enalapril and angiotensin receptor blockers (ARBs) like losartan are frontline therapies for managing heart failure and post-myocardial infarction care." (PMID 37965396, 2023). "In patients with heart failure or cardiac dysfunction, ACE inhibitors and beta-blockers are the recommended antihypertensive drugs." (PMID 36836722, 2023). "This is important because women with heart failure experience twice higher rates of adverse events (e.g., ACE inhibitor cough) from medication compared to men." (PMID 36937911, 2023). "The majority of patients with reduced LV function received a sufficient pharmacological heart failure treatment consisting of ACE inhibitor or AT blocker (87.3%), beta-blocker (87.3%), mineralocorticoid receptor antagonists (45.5%) and diuretics (92.7%)." (PMID 35369337, 2022).
heart failure (continued). "The role of “standard” heart failure therapies including ACE inhibitors, beta blockers and sacubitril/valsartan remains uncertain in ATTR-CM." (PMID 36741843, 2022). "ACE inhibitors have been used for decades as a treatment for arterial hypertensionand they improve outcomes in heart failure and chronic renal patients by decreasingANG II levels (14-, 16)." (PMID 35319673, 2022). "The angiotensin receptor-neprilysin inhibitor (ARNI), sacubitril-valsartan has been shown to have beneficial effects beyond ACE inhibitors and ARBs in the treatment of heart failure." (PMID 35528842, 2022). "ACE inhibitors were estimated to lead to the lowest rates of heart failure onset and beta blockers the highest rates of heart failure onset relative to the other antihypertensives." (PMID 35689299, 2022). "In all cases, guideline-directed heart failure treatment was started with betablockers, ACE inhibitors, and diuretics, as well as IV dopamine and tolvaptan in one severe acute heart failure case." (PMID 36142866, 2022). "The magnitude of improvement was similar to that observed in the same canine heart failure model after long-term therapy with ACE inhibitors and/or beta-blockers." (PMID 34623544, 2022). "A previous study of patients with heart failure demonstrated that, despite ACE inhibitor therapy, Ang II concentrations remained persistently higher than those seen in healthy individuals in half of the study population." (PMID 35955981, 2022). "Therapeutic compounds such as beta-blockers or ACE inhibitors are considered to have “durable effects” in heart failure if the elicited benefits remain evident and dissipate only gradually, within days or weeks, after the withdrawal of therapy." (PMID 34623544, 2022). "For other indications, such as heart failure, ACE inhibitors should be scaled down with a careful supervision of the clinical picture." (PMID 35629281, 2022). "Medical treatment of heart failure includes drugs such as ACE-inhibitors, beta-blockers, diuretics, mineralocorticoid receptor antagonists, and SGLT (sodium-glucose cotransporter) 2 inhibitors." (PMID 35336822, 2022). "Enalapril is an ACE inhibitor (ACEI) commonly administered off-label to young children with heart failure by using extemporaneous formulations." (PMID 35745735, 2022). "ARBs have more complete blockade of angiotensin II actions compared with ACE inhibitors, so they are a substitute for the latter in treating patients with heart failure and noticeable ACE inhibitors side effects." (PMID 36127740, 2022). "The benefits of treatment on heart failure outcomes are insofar high based on current evidence when compared to other therapies used for heart failure management including ACE inhibitors." (PMID 36553880, 2022). "The most commonly listed medicines for heart failure were digoxin, ACE inhibitors and loop diuretics." (PMID 36482421, 2022). "Our finding that ACE inhibitors were most effective at preventing heart failure contradicts the ALLHAT randomized trial, which found that thiazide diuretics were most effective in a high cardiovascular risk population." (PMID 35689299, 2022). "Patients with severe heart failure should continue with ACE inhibitors as long as possible with the lowest possible dose for optimal symptom relief, if the patient can take tablets." (PMID 35629281, 2022). "In an early state of pacing-induced heart failure, the vasoconstrictor effect of angiotensin was attenuated and the bradykinin-dependent vasodilator effect of the ACE inhibitor enalapril enhanced, supporting the notion of an increased nitric oxide formation." (PMID 35024969, 2022). "In medical practice, ACE inhibitors are known to reduce the hospitalization incidence for heart failure as they increase life expectancy, exercise tolerance, and life quality." (PMID 36296344, 2022). "The patient was receiving treatment for heart failure (ACE inhibitor, spironolactone) and salbutamol for sinus bradycardia." (PMID 35328031, 2022).
heart failure (continued). "The patient was then treated with anti-heart failure medications (maximum dosages), such as beta-blockers, ACE inhibitors, and diuretics." (PMID 36051285, 2022). "Beta blockers and ACE inhibitors/sartans are strongly indicated in the treatment of heart failure and have beneficial effects on mortality in acute TAAD." (PMID 36062037, 2022). "The girl received treatment for heart failure (ACE inhibitor, spironolactone) and salbutamol due to sinus bradycardia." (PMID 35328031, 2022). "Drugs that are used for heart failure treatment (e.g., ACE inhibitors) potentially affect the renal prognosis in AKI." (PMID 35178254, 2022). "On the other hand, ACEi medication is particularly effective in patients with heart failure with reduced ejection fraction (HFrEF), suggesting an important role for ACE in the heart." (PMID 34359878, 2021). "All patients were receiving state-of-the-art heart failure medication, including beta-blockers (93%), aldosterone antagonists (86%), ACE inhibitors/angiotensin II receptor blockers (31%), or sacubitril/valsartan (68%)." (PMID 34222382, 2021). "For example, beta-blockers and ACE inhibitors are recommended after an MI contingent on heart failure and left ventricular dysfunction." (PMID 33972336, 2021). "Heart failure therapy including ACE inhibitors and/or beta-blockers was initiated early and 82% recovered from cardiotoxicity at least partially." (PMID 34117981, 2021). "Collaborative Group on ACE Inhibitor Trials Overview of randomized trials of angiotensin-converting enzyme inhibitors on mortality and morbidity in patients with heart failure." (PMID 34346940, 2021). "The expression of ACE2 was increased in a rat model of high-output heart failure, as long as the heart failure remained compensated, likely counterbalancing the enhanced ACE/Ang II/AT1R axis." (PMID 33805760, 2021). "The levels of Ang II have been found to be elevated in optimally treated (using ACE blockers or ARB) patients of heart failure, thus adding to the adverse health effects." (PMID 34122129, 2021). "All patients received optimized medication for heart failure, including beta blocker (92%), ACE inhibitor (80%), and diuretic (86%)." (PMID 33200285, 2021). "In contrast to guidelines for management of heart failure patients in the general population, cardio-oncology guidelines recommend LVETx with ACE inhibitors and β blockers for asymptomatic and mild LVD in the setting of cardiotoxic chemotherapy." (PMID 33766148, 2021). "Conventional therapies for the treatment of heart failure, such as the application of β-blockers, angiotensin-converting enzyme (ACE) inhibitors, and aldosterone antagonists are beneficial for patient survival." (PMID 34884805, 2021). "The recommendation of combining ACE inhibitors with isosorbide dinitrate and hydralazine is based on the African American Heart Failure Trial (A-HeFT), demonstrating a 4% improved survival and a 33% reduction in first HF hospitalization in HFrEF patients." (PMID 34640427, 2021). "The phenomenon, often referred to as escape from ACE inhibition or simply “ACE escape”, is right now well recognized, notably pronounced during prolonged treatment and with concomitant disorders such as heart failure." (PMID 34079459, 2021). "By the time of discharge, heart failure therapy consisted of beta-blocker (94.3%), angiotensin converting enzyme (ACE)-inhibitor or angiotensin receptor blocker (ARB) (80%), mineralocorticoid-receptor antagonist (MRA) (45.7%) and loop diuretics (91.4%)." (PMID 33555408, 2021). "In heart failure, it has been demonstrated that soluble ACE2 levels are increased, but there is a paucity of data on the effects of ACE inhibitors on the expression of membrane‐bound cardiac ACE2 in heart failure." (PMID 34390216, 2021).
heart failure (continued). "In view of the risk of myocarditis in the ongoing COVID‐19 pandemic, it is essential to understand expression of membrane‐bound ACE2 in vulnerable subgroups such as heart failure patients and to assess the effects of pharmacological ACE inhibition." (PMID 34390216, 2021). "Among respiratory conditions other than asthma, ACE inhibitor-induced cough was the most common cause (23.3%), followed by COPD (16.4%), GERD (16.4%), and heart failure (15.1%), respectively." (PMID 34284535, 2021). "Beta-blockers, ACE inhibitors and ARBs should be prescribed according to MI and heart failure guidelines." (PMID 34945221, 2021). "Most of the dogs in the CHF group were on standard heart failure treatment, which included combinations of diuretics, phosphodiesterase-3-inhibitor and ACE-i." (PMID 33499156, 2021). "In line with this, the production of vascular ROS measured by fluorescence oxidative microtopography was increased in heart failure mice and improved with ACE inhibition." (PMID 33807982, 2021). "It is well known that ACE inhibitor and beta-blocker are helpful for the treatment of heart failure." (PMID 33266491, 2020). "The optimal use of diuretics, ACE inhibitors, beta-blockers, and standard treatment with digoxin for heart failure can significantly reduce circulating TNF levels." (PMID 33273955, 2020). "In stage C patients compared withthose in stage A, genotypes DI or DD of the ACE I/D polymorphismwas more prevalent in patients with heart failure; p = 0.02, DIgenotype: OR = 2.52 [CI = 1.13 - 5.59] and DD genotype: OR = 2.59 [CI = 1.12 -5.95]." (PMID 32638886, 2020). "Patients with heart failure were treated with various inotropic agents such as β-blockers, diuretics, and angiotensin-converting enzyme (ACE) inhibitors." (PMID 32083094, 2020). "We also statistically adjusted our analysis for the use of other medications that are commonly used for heart failure, including beta-blockers, ACE-inhibitors, and ARBs." (PMID 32334617, 2020). "Several randomized clinical trials demonstrated the beneficial effect of ACE inhibitors, mineralocorticoid receptor blockers, and AR blockers in the management of heart failure patients." (PMID 33488934, 2020). "Currently, there is no recommendation for stopping angiotensin receptor blockers/ACE inhibitors, especially for patients with heart failure." (PMID 33195443, 2020). "It includes the use of beta-blockers and angiotensin-converting enzyme (ACE) inhibitor/angiotensin receptor blocker in patients with heart failure and antiarrhythmic agents (amiodarone) in case of malignant arrhythmias." (PMID 33003425, 2020). "Of great interest, the PARADIGM-HF clinical trial showed that angiotensin-neprilysin inhibition was superior to the ACE inhibitor enalapril in patients with heart failure with reduced ejection fraction." (PMID 33126450, 2020). "For instance, described by numerous literatures, drugs treating heart failure such as diuretics, ACE inhibitors andAT1R blockers would impact inflammatory pathway." (PMID 33240107, 2020). "The prescribed heart failure medication included beta-blockers, loop and mineralocorticoid diuretics, digoxin, angiotensin-converting enzyme (ACE) inhibitors, and proton pump inhibitors." (PMID 32138751, 2020). "Numerous trials with classical heart failure therapies (beta blockers, angiotensin-converting enzyme (ACE) inhibitors, ARBs) have been undertaken to prevent cardiotoxicity." (PMID 32964378, 2020). "In particular, a number of providers felt that it was their responsibility to deliver evidence-based care, including for an ACE inhibitor in heart failure." (PMID 30994460, 2019). "Currently, patients with HFrEF benefit from heart failure cocktail medications like beta-blockers, angiotensin-converting enzyme (ACE) inhibitors, angiotensin receptor type 1 antagonists, aldosterone receptor antagonists, diuretics, and digoxin." (PMID 31205834, 2019).
heart failure (continued). "In ischaemic heart disease, ACE inhibitors and beta-blockers can be given to reduce further coronary events as well as morbidity and mortality related to heart failure." (PMID 30429050, 2019). "ACE inhibitors and β blockers along with antithrombotics are recommended in patients with stage B, C heart failure (grade A, EL 1)." (PMID 33061064, 2019). "According to the 2014 JSH guidelines, ARBs or ACE inhibitors are recommended for patients with heart failure, whereas CCBs require careful use." (PMID 30842611, 2019). "A total of 66 patients with heart failure and reduced ejection fraction already on guideline-recommended target dose ACE inhibitors or ARBs (equivalent to enalapril 10 mg twice daily) were switched to maximum-dose sacubitril-valsartan (200 mg twice daily)." (PMID 31772613, 2019). "This has been successfully demonstrated in many heart failure trials on ACE-inhibition and angiotensin receptor blockade." (PMID 31032264, 2019). "The systolic dysfunction should be countered by blocking the neurohormonal arcade leading to heart failure by initiating angiotensin-converting enzyme (ACE) inhibitors, angiotensin receptor blockers (ARB), beta-blockers, and diuretics." (PMID 31511802, 2019). "These insights in patients with stable ischemic heart disease were also noticed in heart failure patients, who only benefited from ACE inhibition in case of elevated FGF23 levels." (PMID 31540546, 2019). "The possible reason for doctors' good adherence to guidelines while treating patients with heart failure seems to be the wide range of antihypertensive classes (diuretics, ACE inhibitors, BB, ARB, and aldosterone antagonists) recommended by guidelines." (PMID 29721335, 2018). "Regarding drug treatment, a positive effect on heart failure was reported for beta-blocking agents (14/44 = 32%), ACE inhibitors (6/40 = 15%), calcium-channel blockers (1/37 = 3%) and diuretics (3/39 = 8%)." (PMID 30025539, 2018). "The angiotensin receptor neprilysin inhibitor valsartan/sacubitril should replace ACE inhibitors/ARBs in patients with persistent heart failure symptoms despite optimal medical heart failure therapy including ACE inhibitor/ARB, a beta-blocker, and an MRA." (PMID 29767811, 2018). "This drug has proven to be more effective in the treatment of heart failure than traditional Angiotensin-converting enzyme (ACE) inhibitors." (PMID 29385089, 2018). "Then, heart failure therapy followed with angiotensin-converting enzyme (ACE) inhibitor (enalapril), beta blocker, diuretics, and digoxin." (PMID 30404652, 2018). "All of these drugs have an impact on morbidity and mortality: ACE-inhibitors, beta-blockers and spironolactone reduce death and hospitalization by about one third each, the latter in patients with severe heart failure only." (PMID 30586432, 2018). "ACE inhibitors and beta-blockers are most used drugs to prevent remodeling after MI and progression to heart failure." (PMID 28230797, 2017). "The deleterious effects of sustained RAAS activation on the development of heart failure are counteracted by angiotensin-converting enzyme (ACE) inhibitors, angiotensin II receptor blocker (ARB), and mineralocorticoid-receptor antagonist (MRA)." (PMID 29152151, 2017). "Aliskiren, either used alone or combined with standard medical therapies containing ACE inhibitor or ARB, is associated with more adverse events including hypotension, renal dysfunction, and hyperkalaemia in heart failure patients." (PMID 29152151, 2017). "Large cross-sectional population studies have found, for instance, that beta-blockers and ACE-inhibitors are prescribed in 86 and 65% of patients with coronary disease and in 93 and 71% of patients with heart failure, respectively." (PMID 28856537, 2017).